COG8 (component of oligomeric golgi complex 8)
Description:
Required for normal Golgi function.
Synonyms: FLJ22315; DOR1; CDG2H
Tractability: Antibody: UniProt places it where antibodies can reach, with high confidence. PROTAC: ubiquitination databases record sites on it; its protein half-life has been measured.
Target class: Other cytosolic protein
Gene: Protein-coding gene on chromosome 16 (69,320,140 to 69,339,583, reverse strand). Ensembl gene ENSG00000213380.
Subcellular location: Golgi apparatus membrane
Subcellular location (Human Protein Atlas): Golgi apparatus
Pathways (Reactome):
Vesicle-mediated transport: COPI-mediated anterograde transport; Intra-Golgi traffic; Retrograde transport at the Trans-Golgi-Network
Gene Ontology:
Molecular function: protein binding
Biological process: Golgi organization; retrograde transport, vesicle recycling within Golgi; intra-Golgi vesicle-mediated transport
Cellular component: Golgi apparatus; Golgi transport complex; membrane; Golgi membrane; trans-Golgi network membrane
Genetic constraint (gnomAD): Loss-of-function variants: 45 observed, 45.91 expected, observed/expected ratio (o/e) 0.98, 90% interval 0.77 to 1.26. The upper end of that interval is the gene's LOEUF score, 1.26, which puts it in group 5 of 6, group 1 being the genes least tolerant of losing a copy. Missense variants: 793 observed, 845.84 expected, observed/expected ratio (o/e) 0.94, 90% interval 0.88 to 0.99. Synonymous variants: 407 observed, 355.28 expected, observed/expected ratio (o/e) 1.15, 90% interval 1.06 to 1.24.
Gene-disease validity (ClinGen):
ClinGen rates the evidence that COG8 causes each of these diseases.
COG8-congenital disorder of glycosylation (autosomal recessive): Definitive. The CDG (Congenital Disorders of Glycosylation) syndromes are a group of autosomal recessive disorders affecting glycoprotein synthesis.
Homologues: Orthologues: chimpanzee COG8 (99% identical), macaque COG8 (97% identical), rat Cog8 (90% identical), guinea pig COG8 (89% identical), mouse Cog8 (89% identical), dog COG8 (87% identical), rabbit COG8 (85% identical), pig COG8 (81% identical), tropical clawed frog cog8 (69% identical), zebrafish cog8 (67% identical), Drosophila melanogaster Cog8 (40% identical), Caenorhabditis elegans cogc-8 (13% identical).
Diseases named in the same sentence as COG8 in open-access papers:
COG8 is named in the same sentence as 5 diseases in open-access papers, as found by Europe PMC text mining. Sharing a sentence is not in itself a finding about the gene and the disease. The quoted sentences say what the papers report.
tumor (3 papers, 2020 to 2023). "Similarly, high mRNA expression of 5 of all COG isoforms (COG2, COG3, COG5, COG6, COG7, and COG8) was also correlated with favourable OS of KIRC patients with tumour grade 2, grade 3, and grade 4, while patients with low mRNA expression of COG4 showed higher survival rate." (PMID 34539936, 2021). "mRNA expression levels of COG subtypes depended on the tumour grade, especially COG4, COG5, COG6, COG7, and COG8." (PMID 34539936, 2021). "The reduced clonogenic growth of MDA-MB-231 herein may be attributed to the upregulation of some tumor suppressor proteins such as TSPAN6, MAPK6, SPRY2, HAUS4, stomatin (STOM) and conserved oligomeric golgi complex subunit 8 (COG8)." (PMID 38283944, 2023).
skeletal dysplasia (1 paper, 2021). Any Mendelian diseases that affects growth and development of the skeleton. "Skeletal dysplasia was also reported as the main clinical feature of patients with COG7-CDG, COG1-CDG and COG8-CDG." (PMID 34441372, 2021). "While patients with COG8-CDG displayed severe skeletal dysplasia, COG1-CDG and COG8-CDG patients had a significantly milder clinical presentation." (PMID 34441372, 2021).
COG8 also shares sentences with these, for which no sentence is quoted: dermatomyositis (1 paper); primordial dwarfism (1); schizophrenia (1).